IL1B (interleukin 1 beta)
Diseases named in the same sentence as IL1B in open-access papers (continued):
Sharing a sentence is not in itself a finding about the gene and the disease.
epilepsy (continued). "The α-asarone role in the mitigation of the learning and memory deficits as induced by epilepsy, as presented in our study, might be explained by the α-asarone effects on IL-1β and TNF-α production." (PMID 29312110, 2017). "Considering the high cooccurrence of epilepsy and T1D, it is possible that the commensal microbiota drive autoimmune epileptogenesis through expansion of Th17 cells mediated by spontaneous secretion of proinflammatory cytokines, for instance, IL-6 and IL-1β." (PMID 27882059, 2016). "Moreover, a recent study shows over-activation of IL-1β signaling pathway in astrocytes before epilepsy onset in a mouse model of TSC, pointing to the role of mTOR-mediated inflammatory mechanisms in TSC." (PMID 27122151, 2016). "In addition, IL-1β can aggravate the occurrence and development of epilepsy and can rapidly lower the focal ictal event threshold." (PMID 26925269, 2016). "IL-1β has been hypothesized to contribute to the pathogenesis of epilepsy, and anti-IL-1β medication has been hypothesized to have therapeutic potential as AED." (PMID 24757498, 2014). "A significantly higher IL-1β expression was observed in tumor tissue of patients with epilepsy." (PMID 23270518, 2012). "In a variety of animal models of epilepsy, as well as in patients suffering from epilepsy, increased elevations of pro-inflammatory cytokines IL-6, IL-1β and TNF-α have also been found in the cerebrospinal fluid, and many of these cytokines have been shown to have proconvulsant activity." (PMID 20067608, 2010). "However, the IL-1β and IL-6 transcript levels were still significantly elevated (222.8 ± 35.2% and 117.1 ± 2.1% of those in the respective controls) at 7 weeks post-SE during the chronic phase of epilepsy." (PMID 41445743, 2025). "IFN‐ γ and IL‐1β may become important markers for diagnosing drug‐resistant epilepsy in children." (PMID 40103702, 2025). "A prospective study of epilepsy outcomes showed that serum levels of IL-1β showed a significant correlation with the measures of disease severity and the number of anti-seizure medications used and a negative correlation with the age of disease onset in children with epilepsy." (PMID 35837232, 2022). "In addition, glucocorticoid therapy has achieved the prevention and treatment of epilepsy and epileptic encephalopathy by directly inhibiting the expression and release of IL‐1β and TNF‐α,12, 13 but has serious side effects (such as hypertension and osteoporosis)." (PMID 36301030, 2022). "However, dogs with epilepsy have increased serum IL-1β levels, regardless of the underlying cause of the disease." (PMID 35837232, 2022). "Interestingly, the proinflammatory cytokines IFN-γ, IL-1β and IL-6 were negatively correlated with the age of disease onset in children with epilepsy, suggesting that younger patients demonstrated a more aggravated inflammatory response to recent seizure attacks." (PMID 32151248, 2020). "Thus, serum IL-1β may be specific to neuroinflammation for epilepsy development, implicating it as a prognostic biomarker for epilepsy." (PMID 32151248, 2020). "However, dogs with epilepsy had increased levels of IL-1β in serum (p = 0.003) regardless of the underlying cause of the disease (p = 0.0045)." (PMID 31208341, 2019). "Also, among the presumed idiopathic epilepsy cases, single dogs with very high levels of IL-1β, could in fact have immune-mediated epilepsy which needs more in-depth research." (PMID 31208341, 2019). "Increased IL-1β levels were detected in the peripheral blood in dogs with idiopathic and structural epilepsy leading to the assumption that there is an involvement of inflammation in pathophysiology of epilepsy which should be considered in the search for new therapeutic strategies for this disease." (PMID 31208341, 2019).
epilepsy (continued). "In addition, increased proinflammatory cytokines were found in the serum and CSF in patients with epilepsy, whereas the analysis of human brain specimens from drug-refractory epileptic patients showed strong activation of the IL-1b/IL-1R1 system in brain resident cells, such as in glia and neurons." (PMID 20863362, 2010). "Quantitative PCR revealed that IL-1β, IL-6, and TNF-α mRNA levels were markedly elevated in the PBS-treated epilepsy group but significantly suppressed in the L. eligens-treated epilepsy group." (PMID 41356796, 2026). "Blood and brain tissues were collected for biochemical assays (SUR1, TRPM4, IL-1β, IL-6, TNF-α, TAS, TOS, OSI, thiol-disulfide homeostasis), histological analyses (H&E, Cresyl Violet, and 8-OHdG immunostaining), and qRT-PCR of epilepsy-related miRNAs." (PMID 41718951, 2026). "Laboratory studies from epilepsy have shown that the levels of inflammasomes (NLRP1, NLRP3, caspase 1, IL-1β, ASC, AIM2, gasdermin D, IL-18, intracellular calcium ion, sTNFr2) were also elevated." (PMID 40217546, 2025). "In our study, we observed a marked increase in the expression levels of key inflammatory markers, specifically NFκB, IL‐1β, and TNF, in rats diagnosed with epilepsy." (PMID 41523603, 2025). "Primary outcome measures included epilepsy latency, Morris water maze escape latency, oxidative stress markers (MDA, GSH, SOD), inflammatory factors (IL-1β, TNF-α), and Glial fibrillary acidic protein (GFAP)." (PMID 40709096, 2025). "In this review, we mainly focus on the IL-1β/IL-1R1/IL-1Ra pathway and HMGB1/TLR4 pathway, in which recent advances in knowledge have been made for epilepsy." (PMID 41155637, 2025). "In our research on epilepsy development, we concentrated on how EGCG influences the expression of inflammatory proteins TNF‐α and IL‐1β." (PMID 41523603, 2025). "Towards clinical translation, we carefully reviewed existing substances and drugs targeting the IL-1β/IL-1R1/IL-1Ra pathway and HMGB1/TLR4 pathway and their effects on epilepsy models and patients." (PMID 41155637, 2025). "Previous studies in epilepsy patients treated with VNS have shown that incubating whole blood with endotoxin results in a significantly reduced release of TNF‐α, IL‐1β, and IL‐6 4 h post‐VNS." (PMID 39903575, 2025). "In a mouse model of pilocarpine-induced epilepsy, four studies consistently show that inflammation is enhanced through NLRP3, caspase 1, ASC, gasdermin D, IL-1β, and IL-18 pathways." (PMID 40217546, 2025). "The elevation of inflammatory mediators, including IL-1β, TNF-α, and IL-6, was initiated 2 h following seizures and increased to the highest concentration between 6 and 12 h following seizures in the epilepsy mouse model." (PMID 39723425, 2024). "Extensive research has confirmed that excessive activation of astrocytes and the subsequent release of various pro-inflammatory cytokines, such as IL-1β, IL-6 and TNF-α, are considerably involved in the pathogenesis and progression of epilepsy." (PMID 39598325, 2024). "Consistent with our findings, liraglutide reduced IL-1β and TNF-α levels in a rat model of PTZ-induced epilepsy, highlighting the NLRP3 inflammasome complex as a potential target for antiepileptogenic treatments." (PMID 39457518, 2024). "Increasing evidence indicated that major proinflammatory cytokines, including IL-1β, TNF-α, and IL-6, were upregulated in epileptic patients and animal models of epilepsy." (PMID 38087170, 2024). "In a study, diclofenac decreased IL‐1β and TNF‐α values in brain homogenates in the kindling epilepsy model created with pentylenetetrazol." (PMID 37688418, 2023). "In addition, IL-1β may increase neuronal excitability by down-modulating the astrocytic glutamate transporter (GLT-1), which results in impaired glutamate clearance that has been identified as one of the causative factors in drug-resistant epilepsy." (PMID 37895080, 2023).
epilepsy (continued). "The neuroimmune inflammatory response mediated by IL-1β/IL-1R1 and HMGB1/TLR4 signaling pathways plays an important role in the pathogenesis of epilepsy." (PMID 37305762, 2023). "During epileptogenesis and the chronic phase of epilepsy, the hippocampal concentrations of TFN-α and IL-1β increase on days 8, 18, and 28 post-SE, while the IL-6 concentration did not change at any of these three evaluation times." (PMID 37047461, 2023). "In murine models of inflammation, LTG significantly inhibited IL-1β, IL-6, and TNF-α secretion in vivo and in vitro, revealing possible immunomodulatory properties of LTG in epilepsy and BD." (PMID 34791253, 2022). "We observed the upregulation of IL1β and CXCL12 in the early phase of KA-induced epilepsy and elevated levels of CCL5 at a later time point, compared with control animals." (PMID 35326336, 2022). "By regulating miR-203, UCA1 decreases IL-1β, IL-6, TNF-α, and Cox-2 levels via miR-499b-5p in epilepsy." (PMID 35898503, 2022). "Here, miR-8114 expression was increased after IL-1β- and PTZ-induced epilepsy but reduced by HsTx2 treatment." (PMID 36457055, 2022). "HDAC5 silencing or miR-485 mimic reduced the formation of IL-1β, TNF-α, and IL-6 by epilepsy model neurons, and this effect was rescued by HDAC5 overexpression." (PMID 34021541, 2021). "The level of IL-1β and TNF-α in the VPA-resistant group was substantially higher than that in children with VPA-sensitive epilepsy." (PMID 34497517, 2021). "Western blotting in mice hippocampal tissue was carried out, and results indicated that expression of HIF-1α, IL-1β, and TNF-α in the hippocampus of mice with VPA-resistant epilepsy was upregulated compared with that in mice with VPA-sensitive epilepsy." (PMID 34497517, 2021). "The levels of several pro-inflammatory cytokines such as IL-1β, IL-6, and TNF-α are often elevated in cerebrospinal fluid and serum of patients or rats with epilepsy." (PMID 34924959, 2021). "Thirdly, this study found the dysregulation of miR-221-3p, IL-1β, and TNF-α in VPA-resistant epilepsy, and confirmed the influence of these mediators on seizure severity." (PMID 34497517, 2021). "Inflammatory mediators (e.g., Interleukin (IL)-1β, Tumor necrosis factor (TNF)-α) have been found increased in the brain following seizures and during epilepsy in both experimental models of epilepsy and patients." (PMID 34572093, 2021). "Therapies interfering with HMGB1/TLR4, NF-κB, IL-1β, COX-2, PGE2/EP2, and TGF-β signaling pathways, and other inflammatory targets have been proposed to treat epilepsy." (PMID 34830412, 2021). "The most commonly studied IL-1β, IL-6, and TNF-α tend to be potential mediators in the neuropathology of epilepsy." (PMID 34976232, 2021). "Proteomics analysis revealed that overexpressed HIF-1α interacted with IL-1β and TNF-α in mice with VPA-resistant epilepsy, which was also confirmed by western blotting." (PMID 34497517, 2021). "Serum α-synuclein did not showed significant correlation with serum levels of IFN-β, IFN-γ, IL-1β, IL-6, IL-10 and TNF-α in patients with epilepsy and acquired demyelinating disorders of the CNS." (PMID 32151248, 2020). "Numerous studies have shown upregulation of IL-1β, IL-6, and TNF-α in animals with (recurrent) seizures and patients with epilepsy." (PMID 33324329, 2020). "Therefore, IL-1β may mediate the epilepsy-induced sleep disturbances in epileptic patients." (PMID 32793110, 2020). "Activation of the NLRP3 inflammasome has been detected during epilepsy, and knockdown of NLRP3 or caspase-1 decreased IL-1β and IL-16 levels and provided neuroprotection against SE-associated neuronal damage." (PMID 31097691, 2019). "In particular, high levels of proinflammatory cytokine (IL-1β and TNF-α) are found in epileptogenic tissues from mice with epilepsy of various etiologies." (PMID 30922332, 2019).
epilepsy (continued). "In the central nervous system, interleukin (IL)‐1β, IL‐6 and tumour necrosis factor (TNF)‐α have a regulatory role in pathophysiological processes of epilepsy." (PMID 31144434, 2019). "In the context of epilepsy, MAPK are thought to play a role in Cx43 phosphorylation, involving TNF-α, interleukin (IL)-1b and VEGF." (PMID 31887157, 2019). "To reach the epileptogenic stage and perform targeted therapy against epilepsy, we took advantage of the active targeting function of AMT for epilepsy foci to deliver anti-IL-1β mAb across the BBB." (PMID 30514296, 2018). "In an experimental model of epilepsy, deletion of TLR3 limits seizures, reduces levels of cytokines TNF-α and IL-1β, decreases levels of microglial activity, and increases survival rates." (PMID 29764485, 2018). "Serum IL-6, IL-1β, TNF-α, and MIP-1α levels were elevated in AED-resistant epilepsy patients and, in patients undergoing resection of the epileptogenic region, IL-1β, TNF-α, and MIP-1α levels decreased after 8 weeks postoperatively." (PMID 27737716, 2016). "For example, a recent study found that vagus nerve-stimulation (VNS) in epilepsy patients inhibits peripheral blood production of TNF, IL-1β, and IL-627." (PMID 27761024, 2016). "Interventional investigations on the IL-1β/IL-1R1/IL-1Ra and HMGB1/TLR4 pathways showed antiseizure effects, suggesting that these pathways could be therapeutic targets for epilepsy." (PMID 41155637, 2025). "In a mouse epilepsy protocol, the gene expression of P2X7, NLRP3, and IL-1β was increased." (PMID 40732240, 2025). "Interleukin-1β (IL-1β) and tumor necrosis factor α (TNF-α) are important pro-inflammatory cytokines, which are considered to be the among the main cytokines involved in the pathogenesis of epilepsy." (PMID 41154178, 2025). "Elevated concentrations of interleukin-6 (IL-6), interferon-gamma (IFN-γ), and interleukin-17A (IL-17A) have been observed in the plasma during the interictal phase of epilepsy, whereas IL-1β, TNF-α, and IL-10 did not rise in comparison to a healthy group." (PMID 39861097, 2024). "Furthermore, agmatine also attenuated the increase in NLRP3, ASC, caspase-1, and IL-1β expression and immunocontent in the hippocampus, while reducing IL-1β serum levels in mice submitted to a pentylenetetrazol (PTZ) model of epilepsy." (PMID 38474387, 2024). "Proinflammatory factors, such as IL‐1β, IL‐6, TNF‐α, and TGF‐β, were reported to play important roles in epileptogenesis, indicating that inflammatory response in the brain is a crucial mechanism in the pathophysiology of epilepsy." (PMID 38357846, 2024). "Senescent‐like microglia in aged animals demonstrate elevated transcript levels for a range of SASPs, including IL‐10, IL1B, IL‐6, TNFA, and BDNF, all of which may contribute to epilepsy and seizure vulnerability." (PMID 39031751, 2024). "Therefore, we further investigated the levels of serum biomarkers, including SIRT3, IL-6, IL-1β, TNF-α, and CRP in epilepsy patients." (PMID 39091611, 2024). "Proinflammatory factors in the brain, such as interleukin-1β (Il-1β), Il-6, and tumor necrosis factor (TNF-α), initiate downstream inflammatory cascades and lead to impairment of neuronal function, which promotes the occurrence and development of epilepsy." (PMID 37365625, 2023). "IL-1β enhances NMDA-mediated Ca2+ influx into the cell, which may induce the characteristic hippocampal neuronal death seen in epilepsy." (PMID 37895080, 2023). "This outcome could be explained by the decrease of IL-1B and TNF-α levels, reversing the suppressing effects of Pilocarpine (epilepsy inducer) on antioxidant enzymes including SOD, CAT, and GSH." (PMID 36438833, 2022). "Since IL-1β and IL-18 are signaling pathways downstream of NLRP3, our data can indirectly prove that GPR120, as a ligand of NLRP3, regulates the activation of NLRP3 and induces neuroinflammation in epilepsy." (PMID 35624482, 2022).
epilepsy (continued). "Contrary to these results, we did not observe any correlation between IL-1β levels and neurodegeneration assessed by NfH levels in our KA-induced epilepsy model." (PMID 35326336, 2022). "Furthermore, these authors also studied seven adult patients with epilepsy treated with VNS in whom a reduction of IL-6, IL-1β, and TNF blood production was observed." (PMID 36010024, 2022). "We now provide evidence in primary human 3D cultures of constitutive antineurogenic signalling via the IL1-β-IL-1R and HMGB1 RAGE/TLR4 pathways and demonstrate pharmacological reversibility in tissue from patients with severe long-standing drug refectory epilepsy and memory impairments." (PMID 34548070, 2021). "Furthermore, resident glial cells are rapidly activated and trigger the release of proinflammatory cytokines such as interleukin-1 (IL-1β), tumor necrotic factor-alpha (TNF-α), and interleukin-6 (IL-6), which clinically compromise the prognosis of epilepsy." (PMID 34422216, 2021). "In patients with drug-resistant epilepsy, miR-34c-5p was significantly downregulated, which might upregulate high mobility group protein (HMGB1) and IL-1β expression." (PMID 33776649, 2021). "For instance, IL-1β, IL-6, IL-10, IL-2, IL-17, IL-4, and TNF-α were abnormally expressed in patients, whose elevated levels can lead to neuronal degeneration and induce epilepsy." (PMID 33746751, 2021). "Trans-caryophyllene (TC) applied in epilepsy may be attributed to its ability to reduce the expression of pro-inflammatory cytokines, such as TNF-α and IL-1β." (PMID 33746751, 2021). "A higher level of IL1-β was observed in African controls with non-OAE neurological disorders compared to Europeans with epilepsy." (PMID 33799934, 2021). "In rodent models of KA- or PTZ-induced epilepsy, increased levels of seizure behavior, microglial activation markers (Iba-1, TNF-α, IL-1β, IL-6, iNOS, and COX-2), NF-κB activation, apoptosis-related proteins (Bax and caspase-3/8/9) and ROS were confirmed in the hippocampus." (PMID 34680566, 2021). "A higher level of IL1-β was observed in Africans with non-OAE neurological disorders compared to Europeans with epilepsy, p = 0.026." (PMID 33799934, 2021). "It is speculated that epilepsy-driven inflammations may attack circadian clock because inflammatory cytokines (e.g., TNF-α and IL-1β) are modifiers of clock genes, such as Rev-erbα and Per225–27." (PMID 33619249, 2021). "Serum levels of IL-1β showed a significant correlation with measures of disease severity only in children with epilepsy but not in those with acute demyelinating disorders of the CNS." (PMID 32151248, 2020). "Serum levels of IFN-γ, IL-1β, IL-6 and IL-10 showed negative correlation with age of disease onset in pediatric epilepsy patients, suggesting that younger patients demonstrated higher inflammatory responses to afebrile seizure attacks." (PMID 32151248, 2020). "CSF/serum IL-1β levels have been reported as a prognostic factor for epilepsy development after traumatic brain injury, and the brain-specific adhesion molecule ICAM5 can be used to discriminate between drug-responsive and drug-resistant epilepsy." (PMID 32151248, 2020). "We hypothesized that there is an elevation of IL-1β in serum of dogs with TBI as well as in serum and CSF of dogs with epilepsy, reflecting involvement of this cytokine in the pathophysiology of naturally occurring canine epilepsy in a clinical setting." (PMID 31208341, 2019). "The serum and gene expression of the inflammatory cytokines—IL-1α, IL-1β, IL-2, IL-6, IL-8 and TNF-α—showed the highest levels among the “Epilepsy-only” group followed by lower levels in the epilepsy–cannabis users and finally the lowest levels in the healthy controls." (PMID 31757102, 2019). "In addition, the concentration of the IL-1β was also measured in serum of TBI dogs, as these animals tend to develop post traumatic epilepsy." (PMID 31208341, 2019).